FABP7 (fatty acid binding protein 7)
Diseases named in the same sentence as FABP7 in open-access papers (continued):
Sharing a sentence is not in itself a finding about the gene and the disease.
glioma (continued). "All set of data suggest that FABP7 could be a useful of invasion of glioma cells and that targeting FABP7 could interfere with mechanisms of GBM recurrence." (PMID 23284888, 2012). "Since long-chained PUFAs decrease tumor proliferation by increasing free radical production, increase in FABP7 expression of glioma following DHA supplementation could reduce prooxidant effect of DHA in tumors and consequently reduce their anti tumor effects." (PMID 19014610, 2008). "The SF763 glioma cell line was chosen for this study because it had the lowest ratio of nuclear to cytoplasmic FABP7 as compared to other cell lines, and induction of FABP7 nuclear translocation by EGFR activation could be easily detected." (PMID 16623952, 2006). "Since both EGFR activation and forced expression of FABP7 promote glioma cell migration, we examined whether inhibiting the expression of FABP7 can suppress glioma cell migration induced by EGF." (PMID 16623952, 2006). "We characterize the expression of FABP7 in normal brain, gliotic tissues, and glial tumors." (PMID 16623952, 2006). "In addition, we establish an association between nuclear FABP7 and EGFR expression both in human GBM tumors and in a glioma cell line." (PMID 16623952, 2006). "Antisense oligodeoxynucleotides (ODNs) have been successfully used to reduce expression of other members of the FABP family, so we examined whether inhibiting FABP7 expression with ODNs affects glioma cell migration." (PMID 16623952, 2006). "Based on the function of Id4, OLIG1, and OLIG2 during normal development, our data suggest that Id4 and potentially other genes such as Fabp7 and Ptprz1 might account for the formation of distinct glioma subtypes during oncogenic progression." (PMID 16018821, 2005). "Therefore, the expression of survival-associated genes in ODG and OAC can be divided into at least two subgroups; genes such as Olig1 and Olig2 that are expressed in all glial tumors, and genes such as Fabp7 that are restricted to astrocytes." (PMID 16018821, 2005). "FABP7 has been shown to be involved in lipid metabolism in various tumors, particularly gliomas, suggesting that the abnormal expression of FABP7 may influence the prognosis of patients with glioma and their response to treatment with the antiangiogenic agent apatinib." (PMID 35783014, 2022). "However, based upon the expression patterns of FABP7 during the development of central nervous system, in adult brain, and in gliomas, transformation of FABP7-positive cells may contribute to the histogenesis of a subgroup of gliomas." (PMID 16623952, 2006). "Meanwhile, fatty acid flux, FABP7-mediated PUFA transport, and cholesterol uptake reshape the tumor microenvironment, sustain glioma stemness, and promote immune suppression." (PMID 41710656, 2026). "FABP7 inhibitor MF6 can suppress glioblastoma, while supplementation of DHA (a FABP7 ligand) can inhibit glioma migration." (PMID 40717587, 2025). "For instance, Fatty Acid Binding Protein 7 (FABP7) is highly expressed and localized to the nuclei of IDH1-wt compared to IDH-mut gliomas." (PMID 36425564, 2022). "By altering the expression level of FABP7 and the ratio of DHA:AA in malignant glioma cells, it was found that DHA and AA affect migration in an FABP7-dependent manner, with DHA inhibiting migration and AA promoting migration." (PMID 35844236, 2022). "Furthermore, FABP7 was recently found to interact with nuclear factors, such as ACLY and RXRα, to regulate gene expression in astrocytes and glioma cells, influencing cellular metabolism and proliferation." (PMID 39596296, 2024). "In a glioma cell line, NFIA and NFIC siRNAs inhibited and enhanced FABP7 promoter activity, respectively, thus indicating that FABP7 promoter activity in RCC cell lines may be weaker than that in the HEK293 cell line." (PMID 21771320, 2011). "This discrepancy might be attributed to a difference in FABP7 promoter regulation of NFIA and NFIC in RCC cell lines and glioma cell lines." (PMID 21771320, 2011).
glioma (continued). "In glioma cell lines, NFI dephosphorylation is correlated with FABP7 expression." (PMID 21771320, 2011). "Grade I pilocytic astrocytoma is the only type of glioma examined that does not show nuclear FABP7 staining in our studies." (PMID 16623952, 2006). "In other experiments, we noted that immortalized non-tumorigenic astrocytes express similar amounts of FABP7 compared to glioma cell lines (data not shown)." (PMID 16623952, 2006). "For these reasons, FABP7 expression or the presence of nuclear FABP7 alone is unlikely a factor unique to glioma oncogenesis and progression." (PMID 16623952, 2006). "FABP7 overexpression in glioma cells does not affect cell cycle progression and activation of apoptosis." (PMID 16623952, 2006). "Expression of FABP7 in non-tumor brain and glioma specimens was examined using immunohistochemistry, and its correlation to the clinical behavior of the tumors was analyzed." (PMID 16623952, 2006). "The functions of Id4, OLIG1, and OLIG2 during normal development, and our data suggest that Id4 and potentially other proteins such as FABP7 and PTPRZ1 might account for the formation of distinct glioma subtypes during oncogenic progression." (PMID 16018821, 2005). "To date, however, the role of FABP7 in the prognosis of glioma has not been clearly demonstrated." (PMID 35783014, 2022). "In addition, we studied effects of supplementation of these oils on gene expression of FABP-7, EGFR, RXR-α and PPAR-γ as molecular targets of PUFAs through which PUFAs may influence functions of glioma tumors." (PMID 19014610, 2008). "We show that increased FABP7 expression occurs in a subset of reactive astrocytes, that FABP7 expression is restricted to cells of astrocytic lineage in glioma, and that there is almost no nuclear FABP7 immunoreactivity in well-circumscribed pilocytic astrocytoma." (PMID 16623952, 2006). "To investigate possible molecular mechanisms underlying this association, we compared the expression and subcellular localization of FABP7 in non-tumor brain tissues with different types of glioma, and examined the expression of FABP7 and epidermal growth factor receptor (EGFR) in GBM tumors." (PMID 16623952, 2006). "Although suggestive, neither offers a clear explanation of the action of FABP7 in gliomas." (PMID 16623952, 2006). "Four commonly used EGFR-expressing glioma cell lines, U87, U251, SF763, and SF767, were examined for FABP7 expression using immunohistochemistry, and all these lines demonstrated both cytoplasmic and nuclear FABP7 immunoreactivity (data not shown)." (PMID 16623952, 2006).
glioblastoma (28 papers, 2006 to 2025). The most malignant astrocytic tumor (WHO grade IV). "The mechanisms underlying FABP7 effects on glioblastoma cell proliferation and migration are incompletely understood, but several intriguing possibilities have been proposed." (PMID 37207357, 2023). "For example, high expression of FABP7 was found to enhance the proliferation and migration of glioblastoma (GBM) cells and to be associated with poor patient prognosis." (PMID 35783014, 2022). "Compared to nuclear FABP7-negative, immunoreactivity of nuclear FABP7 in EGFR-expressing glioblastoma specimens correlates with poor survival." (PMID 40097417, 2025). "Compared with glioblastoma fast-cycling cells, FABP7 is preferentially expressed in glioblastoma slow-cycling cells (SCCs)." (PMID 40097417, 2025). "FABP7 is highly expressed in glioblastoma tumor stem cells (GSCs) and drives the migration and infiltration of glioblastoma cells through the RXRα signaling pathway." (PMID 40717587, 2025). "FABP7 drives lipid droplet formation and radioresistance in glioblastoma stem cells through the RXRα signaling pathway." (PMID 40717587, 2025). "Kagawa and colleagues have demonstrated that fatty acid-binding protein 7 (FABP7) is highly expressed in the nuclei of Isocitrate dehydrogenase 1 (IDH1) wild-type glioblastoma and promotes tumor proliferation by upregulating Cav-1 expression." (PMID 40243482, 2025). "Functional heterogeneity exists among subtypes: FABP7 drives glioblastoma stem cell migration via RXRα signaling, while FABP5 exhibits context-dependent roles, promoting HCC progression but suppressing colorectal cancer (CRC) through mTOR-mediated autophagy." (PMID 40717587, 2025). "Knockdown of FABP7 by specific siRNA reduces proliferation and migration in glioblastoma derived neurospheres GBMR11 NS and BT150 NS." (PMID 40097417, 2025). "Knockdown of FABP3 or FABP7 in glioblastoma cell line U87 reduces the formation of LDs during hypoxia, decreases cell number after hypoxia-reoxygenation, and impairs spheroid grown." (PMID 40097417, 2025). "Inhibition of FABP7 by the inhibitor SB-FI-26 reduces lipid uptake and storage, which sensitizes glioblastoma SCCs to lower glucose levels and inhibition of migration." (PMID 40097417, 2025). "FABP7 activates nuclear receptor RXRα to drive the migration of glioblastoma stem cell-like cells (GSC), inducing tumor cell chemoresistance and recurrence." (PMID 40717587, 2025). "In glioblastoma cells, FABP7 coordinates the utilization of AA and DHA depending on their relative availability, with an increase in the AA:DHA ratio promoting AA metabolism by COX2." (PMID 37688656, 2024). "In this sense, the inhibition of FASN with the natural antibiotic cerulenin blocks cell proliferation and decreases the expression of the glioblastoma stemness markers Nestin, Sox2 and Fatty Acid Binding Protein 7 (FABP7)." (PMID 36934087, 2023). "In this study, we observed high expression and nuclear localization of FABP7 in IDH1wt glioblastoma (GB)." (PMID 34716958, 2022). "Survival is significantly improved when glioblastoma tumors are treated with FABP7 inhibition combination with 2-DG." (PMID 35006438, 2021). "FABP7 is known to be upregulated in brain tissue, and its function is well studied in glioblastoma cell lines." (PMID 30442117, 2018). "In vitro, proliferation and migration of glioblastoma cells were affected by manipulating either Fabp7 expression or REV-ERBα activity." (PMID 24932636, 2014). "In order to establish a functional link between increased expression of FABP7 in Rev-erbα KO mice and migration of neuronal cells, we looked at the migration properties of FABP7 expressing U-251 MG glioblastoma cells in a transwell migration assay." (PMID 24932636, 2014). "It was also shown, that FABP7 overexpression is correlated with pure glioblastoma histology and that nuclear expression of FABP7 is more specifically associated with more invasive tumors." (PMID 25389781, 2014).
glioblastoma (continued). "The stem cell-like cells grow as neurospheres in culture and in comparison to adherent glioblastoma cells, they express elevated levels of Fabp7 accompanied by elevated migration and proliferation." (PMID 24932636, 2014). "In glioblastoma biopsies, a gene profiling analysis revealed that FABP7 expression is inversely correlated to survival in younger patients." (PMID 23284888, 2012). "In order to validate the observations from the microarray experiments, the level of FABP7 mRNA in different cells from primary and recurrent glioblastoma patients was measured using quantitative real time PCR." (PMID 23284888, 2012). "FABP7 is highly expressed in glia cells throughout development of the nervous system and high FABP7 expression in glioblastomas is related to poor prognosis." (PMID 18826602, 2008). "This suggests glioblastoma with upregulated FABP7 may drive acetyl-CoA production to support lipid synthesis and rapid proliferation." (PMID 40097417, 2025). "Additionally, FABP7 regulates the infiltration of immunosuppressive cell populations within glioblastomas, affecting patient prognosis and survival." (PMID 40717587, 2025). "Irradiation at 2 Gy can increase the expression of FABP7 in glioblastoma-neutrosphere cell lines." (PMID 40097417, 2025). "For example, in glioblastoma, knockdown of FABP7 enhances radiotherapy sensitivity." (PMID 40717587, 2025). "Likewise, the expression of FABP7 in glioblastoma cells promotes cell migration by a mechanism involving increased expression of inflammatory markers and downregulation of PPARγ signaling." (PMID 37688656, 2024). "Uptake of the ω3 PUFA DHA into glioblastoma patient-derived neural stem-like cells was diminished upon FABP7 knockdown, and the FABP7-dependent elevation in the ratio of DHA to the ω6 PUFA arachidonic acid (AA) was associated with a decrease in cell migration rate." (PMID 37207357, 2023). "Indeed, overexpression of FABP7 was shown to increase the proliferation rate of the U87 glioblastoma cell line and of a xenograft model transplanted with these cells." (PMID 37207357, 2023). "Treatment of U251 human glioblastoma cells with AA promoted αSyn aggregation in an FABP7-dependent manner, and a high affinity FABP7 synthetic ligand disrupted the FABP7–αSyn interaction and reduced αSyn oligomerization, thereby rescuing glial cells from cell death." (PMID 37207357, 2023). "In contrast, FABP7wt overexpression increased level of acetyl‐CoA in nuclei and ACLY activity, indicating nuclear localization of FABP7 in glioblastoma may be essential for the production of nuclear acetyl‐CoA through the interaction with nuclear ACLY." (PMID 34716958, 2022). "Protein analyses could be helpful to get more information about the mechanism by which FABP7 progresses glioblastoma." (PMID 32634135, 2020). "In addition, glioblastoma neurospheres express FABP7 at higher levels than those of adherent cells derived from the same tumor." (PMID 28292269, 2017). "In addition, in vitro manipulation of REV-ERBα and FABP7 affected migration and proliferation properties of glioblastoma cells." (PMID 24932636, 2014). "Of note is that Clock is directly regulated by REV-ERBα and therefore agonists for REV-ERBα may not only reduce Fabp7 expression but also Clock levels, which may reduce neurogenesis and lower the potential of glioblastoma development." (PMID 24932636, 2014). "Targeting FABP7 in combination with chemotherapy could represent a new therapeutic strategy for glioblastoma." (PMID 23284888, 2012). "In support of our results, a negative association between FABP7 expression and survival was recently observed for patients with glioblastoma." (PMID 18826602, 2008). "We previously identified brain type fatty acid-binding protein (FABP7) as a prognostic marker for patients with glioblastoma (GBM)." (PMID 16623952, 2006).
glioblastoma (continued). "FABP7 epigenetically reprograms to suppress immune-related genes (e.g., LPCAT3) while upregulating ferroptosis-resistant genes (e.g., BMAL1), helping glioblastoma cells evade immune clearance." (PMID 40717587, 2025). "Specifically, FABP7 enhances caveolae/caveosome formation by inducing histone acetylation at the Cav-1 promoter, but only in IDH1 wild-type glioblastomas." (PMID 40243482, 2025). "In glioblastoma cell culture, proliferation is suppressed by REV-ERBα and its target fatty acid binding protein 7 (FABP7), which is a marker for NPCs." (PMID 35269386, 2022). "Expression analyses have demonstrated FABP7 transcripts in tumors or urine of patients with RCC, as well as in tissues in those with glioblastoma and melanoma." (PMID 21771320, 2011). "The uptake of DHA leads to inhibition of migration in glioblastoma neural stem-like cells A4-004N dependent on FABP7 expression, suggesting increasing DHA content may reduce glioblastoma migration in FABP7-expressing cells." (PMID 40097417, 2025). "Addition of the REV-ERBα antagonist SR8278 increased FABP7 expression and migration of the cells compared to the solvent control DMSO, indicating that suppression of REV-ERBα had a positive influence on the migration properties of U-251 MG glioblastoma cells." (PMID 24932636, 2014). "Melanomas, glioblastomas, and several types of carcinomas, including RCC, overexpress FABP7." (PMID 21771320, 2011). "Therefore we tested in the same glioblastoma cell line whether the REV-ERBα antagonist SR8278 and siRNA against Fabp7 can affect proliferation." (PMID 24932636, 2014). "Primary and recurrent glioblastoma neurospheres were positive for FABP7 expression whereas in the adherent cells no (Ct ≥40) or significantly lower FABP7 expression was observed: normal human astrocytes and normal human neural progenitors were used as controls." (PMID 23284888, 2012). "In brain tumor specimens, expression of FABP7 in primary glioblastoma was inversely associated with survival in a specific age group and nuclear but not cytoplasmic FABP7 protein was associated with EGFR overexpression and shorter survival in glioblastoma patients." (PMID 19014610, 2008). "To investigate the functional role of FABP7, we examined the effects of FABP7 down-regulation with specific siRNA on the invasive and proliferative capacity of glioblastoma derived neurospheres: BT150 NS and GBMR11 NS, derived from a newly diagnosed and a recurrent GBM, respectively." (PMID 23284888, 2012).